TNF (tumor necrosis factor)
Diseases named in the same sentence as TNF in open-access papers (continued):
Sharing a sentence is not in itself a finding about the gene and the disease.
asthma (continued). "Inflammatory cytokines such as TNF-α, IL-1β and IFN-γ play an important role in diseases such as asthma." (PMID 18341691, 2008). "The most important lung diseases affected by TNFα include chronic bronchitis (CB), chronic obstructive pulmonary disease (COPD), asthma, acute lung injury (ALI) and its severe form acute respiratory distress syndrome (ARDS)." (PMID 17034639, 2006). "IFN-γ has many proinflammatory effects and has been shown to play an important role in early childhood asthma through the upregulation of ICAM-1 and the cellular receptor for TNF-α." (PMID 16952309, 2006). "TNF-α is likely a central mediator of airway inflammation and AHR in asthma, regulating inflammatory cell infiltration, locally enhancing vascular permeability, and inducing the release of the chemokines." (PMID 16893457, 2006). "Although the precise mechanism by which TNF-α leads to the pathology in lungs after RSV infection remains unknown, our data and these previous studies suggest a key role for TNF-α in chronic inflammation in the lung and subsequent airway remodeling associated with asthma." (PMID 16893457, 2006). "Increases in TNF-α within 5 hours of RSV infection in our mouse model also suggest a role for this cytokine in the immunopathology of RSV-induced wheeze and asthma development in humans." (PMID 16893457, 2006). "The inflammatory cytokines, IL-1β and TNF-α, and the growth factor, TGF-β1, are thought to play active roles in asthma and emphysema/COPD, and induce the induction of a number of inflammatory mediators by ASMC." (PMID 16359550, 2005). "This meta-analysis suggests that atorvastatin may have beneficial effects in reducing TNF-α, LDL, total cholesterol, and improving respiratory function in specific clinical contexts such as asthma and COPD." (PMID 41555409, 2026). "In addition, Disease subgroup analysis highlighted a prominent reduction in the levels of TNF-α (WMD: − 0.20; 95% CI − 0.34 to − 0.05; I2 = 97.10%) and CRP (WMD: − 0.29; 95% CI − 0.56 to − 0.02; I2 = 74.13%) in asthma patients." (PMID 41555409, 2026). "In addition to Th1/Th2 cytokines, IL-6, CD40L, TNF-α, IFN-γ, MIP-3α, and IL-10 contribute to asthma-related inflammation." (PMID 41155381, 2025). "Moreover, 1,8-cineole downregulated the levels of pro-inflammatory cytokines, such as IL-1β, IL-4, IL-6, IL-13, IL-17A, and TNF-α, in the BALF of animal asthma models sensitized with ovalbumin, house dust mite, and cigarette smoke." (PMID 40244178, 2025). "The median level of TNF-α levels during the pollution period in asthma patients was significantly higher than the non-pollution period with levels of 14.3 (9.3, 27.4) and 11.3 (7.8, 21.1) pg/mL, p = 0.041, respectively." (PMID 40217808, 2025). "Our findings showed that ADAM17, a key downstream effector molecule of TNF-α, impaired AMs phagocytic function by downregulating the expression of the phagocytic receptor CD36, thereby contributing to the pathogenesis of OVA-induced asthma model." (PMID 41181101, 2025). "Furthermore, this study utilized network pharmacology to identify pivotal asthma treatment targets for YKS, including AKT1, TNF, IL1B, EGFR, IFNG, IL4, CASP3, and PTGS2." (PMID 40420184, 2025). "Mendelian randomization was employed to investigate causal relationships between asthma and core targets like AKT1, TNF, and IL1B, revealing a direct causality with AKT1 but not with TNF or IL1B, suggesting their indirect influence on asthma pathways." (PMID 40420184, 2025). "Concurrently, Sema3E KO mice that were subjected to the type-2 low asthma model demonstrated an elevated presence of pulmonary neutrophils, dendritic cells, CD4 T cells, as well as increased levels of IL-17, TNF, IL-1β, CXCL-8, and MCP-1/CCL2 in comparison to their WT counterparts." (PMID 40512736, 2025).
asthma (continued). "Our study demonstrated that PM2.5 exposure could induce higher serum TNF-α, which supported the evidence of inflammation and hypercoagulation in terms of biomarkers in response to PM2.5 inhalation in patients with asthma." (PMID 40217808, 2025). "DiABZI induced an increased release of lactate dehydrogenase (LDH), IFNα, IFNβ, IFNλ, CXCL10, IL‐6 and TNFα protein and overexpression of MUC5AC transcript in healthy epithelial cells sensitized with HDM, and less in epithelial cells from patient with asthma." (PMID 39466641, 2025). "Nonetheless, TNF-α remains an important mediator in non-type 2 (T2-low) asthma and is a potential target for therapy, particularly in cases characterized by neutrophilic inflammation and inadequate response to corticosteroids." (PMID 40564060, 2025). "According to the GRADE system, the certainty of evidence for the asthma daytime and nighttime symptom scores, FEV1, FVC, PEF, and the levels of TNF-α, IFN-γ, and IL-4 was classified as very low, underscoring the need for additional rigorously designed studies to validate these findings." (PMID 41561940, 2025). "In the later asthma model, YCFA-33 administration significantly increased total IgG and IgG1 in serum, reduced OVA-IgE levels and IL-4 levels, decreased neutrophil content and TNF-α expression, and increased IFN-γ levels in lung lavage fluid (p<0.05)." (PMID 40821771, 2025). "“Type-2-low” asthma is characterized by the absence of Th2 biomarkers and the presence of Th1 biomarkers, such as TNF-α, a proinflammatory cytokine involved in various aspects of airway pathology in asthma." (PMID 40703351, 2025). "TNF-α was one of the inflammatory biomarkers of T-helper type 2-low (T2-low) pheno-endotype of severe neutrophilic asthma in which ICS failed to suppress airway inflammation and resulted in ICS-resistant severe asthma." (PMID 40217808, 2025). "At the cellular level, human ASM cells treated with TNF-α, IL-1β, and IFN-γ (imitate the inflammatory conditions in patients with asthma) induced an up-regulation of miR-145-5p and a down-regulation of Krüppel-like factor 4 (KLF4), an inhibitor of smooth muscle cell proliferation." (PMID 38337625, 2024). "Klotho can also inhibit the nuclear translocation of NF-κB and the expression of downstream genes, reducing the release of inflammatory mediators such as interleukin-6 and tumor necrosis factor-alpha, thereby alleviating airway inflammation in COPD and asthma patients." (PMID 38287280, 2024). "Additionally, we examined the levels of inflammatory cytokines in sputum and found that IL‐5, IL‐6, IL‐8, TNF‐α, IFN‐γ, CCL17, CCL22, CXCL10, CCL4, CCL2, IL‐4, IL‐13, and CCL26 were significantly lower in stable asthma than in acute asthma." (PMID 39508721, 2024). "Interestingly, in this study, the E06-induced reduction of both TNF and IFN-γ correlates with a trend for IL-33 reduction, suggesting unique effects of OxPCs in asthma pathophysiology." (PMID 39194564, 2024). "Preliminary research from our group in an asthma model induced with OVA in BALB/c mice showed that CO treatment regulates eosinophils, neutrophils, and the inflammatory markers IL-4, IL-5, IgE, IL-17, TNF-α, and IFN-γ." (PMID 38666018, 2024). "The presence and concentration of proteins such as eosinophilic granule protein-2 (EG-2), granulocyte-macrophage colony-stimulating factor (GM-CSF), tumor necrosis factor-alpha (TNF-α), and interleukin (IL)-8 have been correlated with airway inflammation and asthma severity." (PMID 39195245, 2024). "C. chinensis seed methanol extract can reduce IL-6, TNF-α, NF-κB, COX-2, and IL-1β in asthma." (PMID 39263346, 2024). "In our study, TNF-α and IL-6 levels in BALF and lung tissues of the respective group were examined to reveal whether L6H21 reduces IL-6 and TNF-α levels in mouse asthma model, and positive results were identified in the L6H21 treatment group." (PMID 38245791, 2024).
asthma (continued). "Moreover, chitin microparticles also induce viral-specific immunity in respiratory allergy and asthma by increasing IL-12, IFN-λ, and TNF-α and reducing the production of IL-4." (PMID 39203729, 2024). "Core target analysis showed that SZYQD may directly or indirectly affect asthma through potential targets, such as AKT, IL-6, TNF-α, and EGFR." (PMID 38093206, 2023). "High serum periostin, TNFα, IL-4, IL-5, and the chitinase-like protein YKL-40 levels, as well as low serum IL-37 levels, were associated with exacerbated asthma in nonsmokers." (PMID 37367073, 2023). "Additionally, three asthma drugs undergoing clinical trials were found to interact with FCGR3A, despite targeting TNF (adalimumab and etanercept) and PTGS1/PTGS2 (indomethacin)." (PMID 37875944, 2023). "How asthma impacts TNFα-induced cytokine responses in human lung fibroblasts is not well characterized." (PMID 36760534, 2023). "For example, studies have confirmed that the CHM prescription YPF and its main active compound wogonin may alleviate airway inflammation in asthma by inhibiting PI3K/AKT, IL-17 and TNF-α signaling pathways." (PMID 37680707, 2023). "Apparently, in parallel with the increase of TNF-α and IFN-γ, many inflammatory cells infiltrated the bronchi and perivascular areas in the asthma model group, with inflammatory cell exudation in the bronchial lumen, bronchial epithelial degeneration, and mucosal thickening." (PMID 36937885, 2023). "A case report identified that asthma symptoms may be masked by anti-TNF-α therapy, suggesting that anti-TNF-α may have a therapeutic effect on asthma." (PMID 37377958, 2023). "In pulmonary fibrotic diseases such as asthma, the production of inflammatory factors such as TGF-β and TNF-α usually tend to increase, which could promote the synthesis of CysLTs (CysLT, LTC4, and LTE4)." (PMID 35783527, 2022). "Collectively, our studies show that combined exposure to TNFα and IFNγ impairs corticosteroid sensitivity in ASM and may contribute to persistent symptoms and exacerbations in severe pediatric asthma." (PMID 35578269, 2022). "In addition, the concentrations of IL-4, IL-5, and IL-13, as well as IL-1β, IL-6, and TNF-α, were greatly elevated in BALF and lung tissues, especially in lung tissues, of asthma mice, which were suppressed after the treatment of Ferr-1 and/or 3-MA." (PMID 35154576, 2022). "Moreover, they illustrated that PTEN expression levels are inhibited by the increased expression of Notch1 via Hes1 in TNF-α-induced ASMCs, which facilitates ASMC proliferation, migration, and airway remodeling in asthma." (PMID 35814272, 2022). "In addition, the contents of TNF-α, TNFR2, CXCL-9, CCL-12, CCL-9, CCL-2, and CCL-5 in the asthma model group were higher than those in the control group, while the contents of GM-CSF and IL-1α were decreased." (PMID 35600943, 2022). "In particular, IL-35 inhibited TNF-α-induced bronchial epithelial cell pyroptosis via the p38 MAPK signaling pathway, which may provide a more detailed pathway for the study of asthma inflammation." (PMID 35034554, 2022). "Furthermore, it was found that the levels of TNF-α, IL-1β, IL-4, IL-5, and IL-13 in the BALF, and the levels of IL-17, IL-6, and OVA-specific IgE were observably increased in serum of RSV-infected asthma mice, while the level of IFN-γ was decreased." (PMID 36213326, 2022). "However, we found that TNF-α and IL-6 in both asthma and COPD patients showed a tendency to decrease after administration of herbal medicines, and IgE in the asthma group showed a comparable decrease after 12 weeks." (PMID 35677382, 2022). "Previous studies have found that both TNF, SPI1, and CCR7 were up-regulated in severe asthma." (PMID 35645813, 2022). "The pro-inflammatory mediators IL-6, TNF-α, and CXCL8 consequently entail the infiltration of activated immune cells, such as mast cells, DCs, and lymphocytes, which are involved in the pathogenesis of asthma." (PMID 35743888, 2022).
asthma (continued). "Increased expression of tumor necrosis factor a (TNF-α in macrophages in T2-high severe asthma has also been described, despite it not being considered a T2 cytokine." (PMID 35330333, 2022). "TNF-α and IFN-γ contribute to the progression of Th2-low asthma." (PMID 36078171, 2022). "Expression of the cytokines TNF-α, IL-1β, IL-6, IL-5, and IL-8 were increased in placentae of female, but not male fetus, in pregnancies complicated by asthma." (PMID 36046194, 2022). "According to the prediction results of network pharmacology, IL-6, TNF, CXCL8, IL-10, IL-1β, and IL-4 may be the key targets of Danlong Dingchuan Decoction against asthma." (PMID 35186104, 2022). "Nevertheless, the efficacy of simultaneous pharmacological inhibition of TNF and IL-6 in asthma was not yet studied." (PMID 35408882, 2022). "Furthermore, the inability of corticosteroids to reduce TNFα/IFNγ-induced VCAM1 and antigen presenting genes implicate ASM-T cell interactions in persistent airway inflammation and thickening in severe asthma." (PMID 35578269, 2022). "Altogether, we concluded that combined inhibition of TNF and IL-6 more effectively reduces the inflammatory response in the lungs as compared to neutralization of these cytokines individually in acute HDM-induced mouse model of asthma." (PMID 35408882, 2022). "Finally, progesterone stimulates the production of proinflammatory cells and upregulates the expression of cytokines and proteins such as IL10, IL-1β, IL-5, IL-6, IL-22, IL-4, IL-17A, TNFα, and GATA 3 through the regulation of receptors in asthma." (PMID 35096261, 2021). "When ASM cells were treated with a variety of cytokines found in high levels in the airways of asthma such as TNFα, IL-1β, Th1 (IFN-γ), Th2 (IL-4, IL-9, and IL-13), and Th17 (IL-17) cytokines, only TNF and IL-1β were able to increase pentraxin-3 secretion significantly." (PMID 35387000, 2021). "It is accepted that the overexpression of pro-inflammatory cytokines such as tumor necrosis factor (TNF)-α, interleukin (IL)-17, IFN-γ, TGF-β, and IL-33, contributes to resistance in severe asthma and COPD, together with allergens, pathogens, and cigarette smoke." (PMID 34576214, 2021). "Furosemide decreased the concentration of TNFα in SARS-CoV-2 infected patients, and together with IL-6 in the pre-eclamptic placenta, children with mild asthma, patients with respiratory disorders, patients with urosepsis, or patients with acute decompensated heart failure." (PMID 34768805, 2021). "TNF-α, IL-13, IL-4, IL-17A and CCL2 are found to increase RhoA mRNA expression via NF-κβ and STAT6 signaling pathways activation, leading to airway hyperreactivity in asthma." (PMID 34069141, 2021). "Moreover, recent findings show that TNF-α activates the p38 MAPK signaling pathway, which induces asthma and the development of COPD." (PMID 33777316, 2021). "In our study, CB2 agonist administration in OVA-induced asthma was found to reduce the accumulation of eosinophils, IL-4, IgE and TNF-α, although CB2 antagonist application found no reduction in the amount of these substances." (PMID 32922464, 2020). "Moreover, Th1 cytokines such as TNF-α and IFN-γ are also involved in asthma, with pro - and anti-asthma effects, respectively." (PMID 33123005, 2020). "Moreover, anti-TNF therapy resulted in clinical improvement of AHR, lung function and quality-of-life of patients with asthma, together with a reduction in exacerbation frequency." (PMID 32929606, 2020). "Here, we have analyzed the levels of cytokines such as IL-13, IFN-γ, TNF-α, IL-4, IL-5, and IL-1β and growth factors such as HGF, VEGF, and CSF2 or GM-CSF along with the estimation of serum S1P concentration in asthma patients compared with the healthy controls." (PMID 32637407, 2020).
asthma (continued). "TNFα induced a robust cytokine response in HBECs and so was chosen as the stimulus for primary bronchial epithelial cells; TNFα significantly increased secretion of IL-6 and CXCL8 from both healthy subjects and asthma patients (p < 0.05 for all comparisons)." (PMID 31974640, 2020). "Moreover, astaxanthin reduced the production of pro-inflammatory mediators and cytokines such as nuclear factor-κB (NF-κB), tumor necrosis factor-α (TNF-α), and interleukin-6 (IL-6), and suppresses T lymphocyte activation in asthma patients." (PMID 33374738, 2020). "Similarly, gemcitabine is another candidate drug in the asthma-COPD and its intranasal administration significantly reduces viruses and the inflammation of lungs and the anti-inflammatory cytokines including TNF-α and IL-1b." (PMID 31952466, 2020). "This flavonoid also inhibited the activation of NF-κB and STAT-1 in macrophages, and reduced inflammatory cytokines including; TNF-α, IL-6, IL-1β and PGE2 and also increased inflammatory cytokines in vitro, which it can useful for the treatment of allergic disorders such as asthma." (PMID 33295229, 2020). "Cells of the immortalized murine macrophage cell line RAW264.7 were treated with cytokines that are known to act in the pathology of asthma (CytoMix), i.e. IFNγ, IL-1β, and TNFα in the presence or absence of recombinant Grx2 WT or Grx2 C40S." (PMID 33224135, 2020). "Moreover, we showed that overexpression of PTEN markedly downregulated CD38 expression in TNF-α-stimulated ASM cells and in the OVA-induced mouse asthma model." (PMID 32889801, 2020). "For the epithelial environment stage of asthma (allergic sensitization stage), air exposure to allergens induces the secretion of proinflammatory cytokines (Group 1) in the airway epithelium, such as TSLP, IL-6, IL-8, TNF-α, IL-25, IL-33, and GM-CSF." (PMID 31284537, 2019). "Dexa reduced the level of serum TNF-α compared to the asthma group (P < 0.05) but MYR did not affect it." (PMID 32641957, 2019). "Additionally, several studies have supported a central role for TNF-α in the development of AHR and other features of the asthma paradigm." (PMID 31692453, 2019). "Interestingly, although IL‐27 production was increased in the IfitmF–/– mice compared to WT in our asthma experiments, levels of Il4, IL‐5, IL‐13, IL‐6, IL‐10, IL17, and TNF‐α were all decreased." (PMID 30365177, 2019). "It has been reported that the length of substance P immuno-reactive nerve fibers are increased in airway of allergic conditions such as asthma and that NGF and TNFα secreted by activated mast cells could enhance neuronal outgrowth." (PMID 31275114, 2019). "IL-17, TNF and IFN-γ are produced by different cell types including immune cells and epithelial cells, and are enhanced in pulmonary inflammatory diseases such as asthma and COPD." (PMID 30087279, 2018). "A known player in asthma pathogenesis, TNF-α was used as a stimulus in this study to better model non-Th2 forms of asthma that are often associated with severe outcomes and glucocorticoid insensitivity." (PMID 30300399, 2018). "It is known also that both IL-6 and TNFα can be involved in asthma pathophysiology and allergic diseases, and allergic diseases would appear to be more frequent in OCD patients, giving weight to elevated IL-6 and TNFα levels in some OCD cases." (PMID 30096863, 2018). "As an important driver of inflammation in the bronchial epithelium, we showed that PAF stimulation increased the expression of IL-6, IL-1β, and TNF-α in HSAECs, and this effect was reduced by HSYA, thus potentially attenuating the secretion of inflammatory cytokines in asthma patients." (PMID 30123133, 2018). "Enhanced thrombin generation is driven in asthma by a systemic inflammatory state mediated by IL-6 and to a lesser extent TNFα, however, not periostin." (PMID 28429138, 2017).